ALB (albumin)
Diseases named in the same sentence as ALB in open-access papers (continued):
Sharing a sentence is not in itself a finding about the gene and the disease.
tumor (continued). "ALRI considers lymphocyte, as well as albumin and RAS status, offering insights into the tumor microenvironment and the host's preoperative inflammatory response and nutritional status." (PMID 38910183, 2024). "Imatinib mesylate (STI571), is a selective kinase inhibitor that inhibits the activation of ALB, KIT, PDGFRA, and PDGFRB, thereby inhibiting tumor growth." (PMID 39600645, 2024). "The training cohort (n=176) identified four independent risk factors for recent complications: PNI ≥45 (OR=4.17, P<0.001), Albumin <40 g/L (OR=3.9, P<0.001), ASA score III-IV (OR=6.29, P<0.001), and Tumor diameter ≥5 cm (OR=4.24, P<0.001)." (PMID 39568563, 2024). "No significant variations were found between the two groups in terms of age, sex, albumin, ASA score, BMI, or tumor type (p > 0.05)." (PMID 38091107, 2024). "The ACR combines the benefits of albumin and CEA to provide a more effective reflection of the host’s nutritional status, inflammatory status, and tumor burden." (PMID 39897534, 2024). "A univariate Cox hazard regression analyses identified ascites volume, apart from AFP, albumin, bilirubin, AST, tumor count, and tumor size, as significant prognostic factor." (PMID 39019953, 2024). "X1, X2, and X3 are taken as 1 if tumor diameter is ≤ 5 cm, MVI is present, and albumin index is <35 g/L, respectively." (PMID 39286273, 2024). "When these nanoparticleswere coated with bovine serum albumin (BSA) protein to prevent aggregationand applied to a tumor-bearing mouse, the 19F signal wasdistinctively detectable in the tumor region." (PMID 39151065, 2024). "Proteins in HLH cluster, implying the recovery of tumor-inhibited protein expression after the DBT, participated in lipid binding and antioxidant activity (APOM, CETP, and ALB)." (PMID 38719824, 2024). "The study employed a UHLC-MS/MS method to determine the levels of albumin-bound of legubicin and two metabolites (free Leu-DOX and DOX) in plasma, tumor, and tissue samples." (PMID 38398527, 2024). "Data on patient demographics, recurrence rates, survival times, and tumor marker levels (CEA, CA 19-9, CA 125, AFP, and CRP to albumin ratio (CAR)), disease-free survival duration (DFS), and overall survival durations (OS) were collected and analyzed." (PMID 39371828, 2024). "This is because albumin reflects the nutritional and inflammatory status of the host, whereas CEA reflects the tumor load." (PMID 39897534, 2024). "We investigated a few markers of systemic inflammation, including ANC, ALC, APC, CRP, albumin, and derived scores, like mGPS, NLR and to examine their relation to TME markers, tumor markers and CMS." (PMID 38645565, 2024). "Our FHAB binds to albumin in the serum, which can transport the FHAB-albumin complex to interact with FcRn and GP60 receptors that are often upregulated in tumor endothelium." (PMID 39697343, 2024). "Currently, two anti-tumor drugs—Abraxane® (Bristol-Myers Squibb, Princeton, NJ, USA) and Fyarro® (AADI Bioscience, Pacific Palisades, CA, USA)—are delivered using albumin NPs." (PMID 39070787, 2024). "Together, the results demonstrate that this PTX-GSSG-PEG micelle can effectively inhibit the growth of tumor cells and have increased biocompatibility compared with PTX–Albumin." (PMID 39339214, 2024). "The results showed that serum albumin concentration, histological grading of the tumor, HER2 status, and tumor blood supply changes after two NACT cycles were significantly associated with the PCR rate in BC patients after NACT." (PMID 39013971, 2024). "The 18 variables were age, tumor size, T-stage, N-stage, OTSCC classification, histologic grade, positive lymph nodes, N, L, SIRI, LMR, PLR, SG, WBC, FIB, HCY, albumin, and Na." (PMID 37574562, 2023). "Firstly, univariate analysis in the training cohort showed that gender, AFP, DCP, BCLC stage, tumor number, tumor size, globulin, DBIL, albumin-to-prealbumin ratio (APR), and fibrinogen (Fib) were significantly associated with RFS." (PMID 36936655, 2023).
tumor (continued). "Univariate and multivariate analyses demonstrated that tumor size (adjusted HR 2.13, P<0.001), AFP (adjusted HR 1.67, P<0.001), albumin (adjusted HR 1.67, P<0.05) and PS (adjusted HR 0.61, P<0.001) were predictors of OS." (PMID 37434986, 2023). "Multimarker models such as the Glasgow Prognostic Score (albumin and CRP) seem to have some potential at predicting tumor response to neoadjuvant CRT." (PMID 36766755, 2023). "In another study, nanobody-albumin nanoparticles (NANAPs) were used for the delivery of 17864-Lx-a, a platinum-bound sunitinib analogue multikinase inhibitor, to EGFR overexpressing tumour cells." (PMID 36980527, 2023). "We previously confirmed that albumin is expressed in several of these PDX models using cross-species proteomics and thus is available for packaging by the tumor." (PMID 36470535, 2023). "PTX is encapsulated in albumin-based nanoparticles, accumulated in tumors through receptor-mediated transcytosis, and bound to the overexpressed SPARC protein on the tumor surface." (PMID 37836018, 2023). "Moreover, the new layer of albumin super coating may increase tumor capture of drug-loaded MNCs." (PMID 36986632, 2023). "A multivariate logistic regression analysis for the prediction of early death was performed using the following variables: a smoking history, ECOG PS, the histological type, liver metastasis, tumor size, neutrophils, lymphocytes, sNLR, CRP, and albumin." (PMID 35871700, 2023). "Therefore, albumin combined with lymphocytes could predict the prognosis of tumor patients." (PMID 37173997, 2023). "After conjugation with pamidronate (PAM) and bovine serum albumin (BSA), the SMF800 conjugates exhibited successful in vivo targeting in bone and tumor tissues with low background uptake, respectively." (PMID 38005156, 2023). "A new prognostic model (SBSpib), including the biomarkers albumin, lymphocytes, and one PET parameter, metabolic tumor volume, was developed." (PMID 36765774, 2023). "The PROSASH and PROSASH-II model, which consisted of serum albumin, bilirubin, AFP, macrovascular invasion, extrahepatic spread, and largest tumor size, were built for survival prediction of patients with HCC treated with sorafenib." (PMID 36911686, 2023). "In multivariable analysis, six variables (serum albumin concentration, age, region, eosinophil quintile, MLR quintile, and ALC quintile) were common survival indicators across all tumor types." (PMID 37962239, 2023). "For HCC recurrence, hsCRP/ALB (0.049635) was the most important variable, followed by MVI (0.029197), NLR (0.023358), and Tumor diameter (0.022628)." (PMID 37305570, 2023). "Albumin binds to the secreted protein acidic and rich in cysteine (SPARC), which is overexpressed in most tumor tissues." (PMID 37173721, 2023). "The model to predict early recurrence was composed of the parameters sex, tumor size, tumor number, MVI, albumin-bilirubin (ALBI) grade, and serum AFP." (PMID 37972101, 2023). "The relatively high concentration of the albumin proteinin blood may provide a reason for why a small excess of unlabeledsubstance (100 nmol) did not cause sufficient blocking of tumor uptakein the PD-L1 tumor, e.g., for [64Cu]Cu-5." (PMID 38038981, 2023). "The results indicated that EST altered the levels of tumor markers (AFP, CEA, and anti-dsDNA) and liver biomarker function (ALT, AST, ALP, ALB, and T. protein)." (PMID 37048097, 2023). "Various proteins that are expressed in a higher range in the tumor cells, such as secreted proteins acidic and rich in cysteine (SPARC), easily and very effectively bind to albumin." (PMID 36984244, 2023). "In another study, albumin‐based NPs were conjugated with a short peptide that can bind to transferrin receptors on the BBB and GBM tumor cells." (PMID 37206213, 2023). "In univariate regression analysis, the covariates albumin, bilirubin, AST, INR, focality, and tumor diameter were identified as prognostic factors for median OS, in addition to BMD." (PMID 35986768, 2023).
tumor (continued). "The present study developed a stable, homogeneous, and slow-release albumin nanoparticle that simultaneously carried PIP and PTX to tumor tissue." (PMID 38140044, 2023). "Multivariate logistic regression analysis found age, tumor size, WBC, ALB, and LMR as five independent factors." (PMID 36761960, 2023). "Although the sensitivity of PNI was lower than that of ALB and APPR, it can acquire higher specificity in predicting NPC occurrence, stage, tumour size, and organ metastasis." (PMID 37699964, 2023). "The systemic inflammation score (SIS), based on serum albumin (Alb) and lymphocyte-to-monocyte ratio (LMR), is a novel prognostic tool for some tumours." (PMID 37270496, 2023). "As a widely used drug carrier, human serum albumin (HSA) has good physiological stability, satisfactory biocompatibility, and tumor-targeting capacity and has been widely used clinically." (PMID 36930774, 2023). "We found that orthotopic murine lung tumors were resistant to systemically delivered IL-12 fused to murine serum albumin (MSA, IL12-MSA) because of low IL-12 receptor (IL-12R) expression on tumor-reactive CD8+ T cells." (PMID 37669107, 2023). "In univariate Cox regression analysis, age, tumor size, N stage, TNM stage, PNI, lymphatic invasion, vascular invasion, anemia, ALB, NLR, PLR, and MLR were found to be significant variables for OS." (PMID 37266630, 2023). "The factors included tumor size, tumor number, TBIL, AST, ALT, PLT, CRE, Child-Pugh score, albumin-bilirubin (ALBI) grade, Up-to-7 criteria, AFP, PIVKA-II, and the proposed methylation indexes." (PMID 37760434, 2023). "Herein, we designed and synthesized biocompatible black phosphorus quantum dots encapsulated with human serum albumin (BPQDs@HSA) as immunosensitizers to enhance NK cell activity against tumor cells, thus achieving synergistic tumor inhibition." (PMID 36683155, 2023). "Variables including sex, albumin level, platelet count, MVI, and tumor volume were used to predict early recurrence, with a c-index of 0.69 for the derivation cohort and 0.66 for the validation cohort." (PMID 37972101, 2023). "Overall, laboratory test variables (CRP, PD‐L1 level, dNLR, ALP, ALB, HGB, and WBC) and tumor characteristics (cancer type, prior liver metastasis, and the number of metastatic sites) are the two major factors for mortality prediction." (PMID 35871390, 2023). "Fewer TOLS patients had preoperative jaundice, lower levels of TB, ALT, and INR, higher levels of albumin, earlier T, N, and AJCC tumor stages, a larger extent of hepatectomy, and fewer patients with neoadjuvant therapy." (PMID 37288584, 2023). "We compared the capacity of ALB, PNI, and AAPR to distinguish the NPC TNM classification, including tumour size (> 5 cm vs. < 5 cm), lymph node invasion, distant organ metastasis, and stage (early vs. late stage)." (PMID 37699964, 2023). "The preoperative hemoglobin, albumin, lymphocyte, and platelet (HALP) score, a comprehensive marker of nutritional and immunological status, has been found to be robust for tumor prognosis prediction." (PMID 37809958, 2023). "Radscore showed a significant correlation with height, weight, neutrophils, monocytes, serum albumin, SCC_Ag, HPV, tumor diameter on MRI, FIGO stage, depth of stromal invasion, and LVSI." (PMID 37655103, 2023). "The seven valuable factors, IOSS, age, A/G (Albumin/Globulin), PALB (prealbumin), FIB (fibrinogen), TLN (total lymph node), and tumor size were used to conduct the predictive OS model." (PMID 37334172, 2023). "Six clinical indices were selected (Mann–Whitney U or Chi-suqare test, two-sided p < 0.05), including tumor size, PLT, ALB, GGT, TB, and DB." (PMID 37482600, 2023). "These variables included age, gender, serum TB, albumin, AST, ALT, platelet counts, AFP level, tumor size, and BCLC stage." (PMID 38003232, 2023).
tumor (continued). "This study aimed to determine a safe and efficient dosage for albumin-bound PTX, examine the effect of BBB opening on PTX concentration in tumors, and estimate the effectiveness of this treatment in reducing tumor size and extending life." (PMID 37836018, 2023). "Considering that AST, WBC, PLT, AFP and tumor size were significantly different between patients with PS0 and PS1 as well as that AFP, tumor size and albumin were predictors of OS, we included these variables in the PSM analysis." (PMID 37434986, 2023). "These 18 features were age, tumor size, T-stage, N-stage, OTSCC classification, histologic grade, positive lymph nodes, N, L, SIRI, LMR, PLR, SG, WBC, FIB, HCY, albumin, and Na." (PMID 37574562, 2023). "Multivariate Cox regression analysis revealed that age, tumor–node–metastasis (TNM) stage, perineural invasion, serum albumin level, and MLR were prognostic factors for OS and DFS and constituted the full model." (PMID 37266630, 2023). "Once nab-paclitaxel is in the extravascular space, it can accumulate inside the tumor through the interaction between SPARC (secreted protein acidic and rich in cysteine) and albumin." (PMID 37509639, 2023). "Instead, derivatives of [68Ga]Ga-SB03045 containing an albumin binder to maximize tumor uptake by virtue of extended blood residence could be exploited in the future, as similar approaches have been reported by others to improve the tumor uptake of [68Ga]Ga-FAPI-04." (PMID 37110717, 2023). "In inflammatory responses to the tumor or from the tumor itself, several inflammatory mediators were discharged, containing interleukin-1(IL-1), IL-6, necrosis factor, and acute phase reactants, which might promote albumin escape from capillaries and modulate the production of albumin in the liver." (PMID 36950094, 2023). "AgNPs coated with bovine serum albumin have also been utilized in PTT, and they are able to invoke nearly complete tumor cell death at temperatures above 45 °C while also proving to have inhibitory effects on the angiogenesis of tumor cells." (PMID 37622997, 2023). "Our study demonstrated that the largest tumor size, BCLC stage, treatment at rupture, treatment after rupture, ALB level, TBil level, Cr level, and INR level were the most crucial predictors associated with overall survival." (PMID 36002714, 2022). "In another work, human serum albumin (HSA)-ICG nanoparticles (HSA-ICG NPs) were designed via intermolecular disulfide conjugations, which presented effective accumulation in tumor and long retention time in 4T1 tumor-bearing mice." (PMID 36451698, 2022). "Of all enrolled factors, we identified four as independent predictors of 30-day survival: largest tumor size (LTS; cm), serum albumin (ALB; g/L), total bilirubin (TBil; umol/L), and serum creatinine (SCr; umol/L)." (PMID 36376820, 2022). "Results showed that pretreatment BAN score was significantly correlated with tumor length, pretreatment WBC count, BMI, ALB and NLR." (PMID 35812183, 2022). "Significant differences in BMI, tumor size, PNI, and pre-operative albumin were observed among the groups, primarily in the PS group." (PMID 36428767, 2022). "A univariate Cox hazard regression analyses identified a high splenic volume, low albumin, high bilirubin, high AST, and a large tumor size as significant prognostic factors." (PMID 35394184, 2022). "After the incorporation of bovine serum albumin (BSA), the BSA composite Pt‐CDs (Pt‐CDs@BSA) exhibited larger particle sizes of 50–120 nm with much higher cellular uptake and tumor accumulation than pure Pt‐CDs." (PMID 36307905, 2022). "Patients are divided according to their albumin, bilirubin, AFP levels, and the size of dominant tumor." (PMID 35330436, 2022). "The cut-off values were 141.5 for PLR, 3.06 for fibrinogen, 1.95 for NLR, 51.15 for PNI, 41 for albumin, 4.90 for WBC, 122.1 for hemoglobin, 23.3 for globulin, and 5 for tumor diameter by ROC curve analysis." (PMID 35340978, 2022).
tumor (continued). "CRP and albumin-to-globulin ratio (AGR) significantly correlated with thiols group level and maximal tumor dimension (p < 0.05)." (PMID 35629255, 2022). "Second, there were some differences in the preoperative characteristics, such as tumor size, CTP, PT INR, and albumin, between the two groups." (PMID 35744000, 2022). "Univariate analyses revealed that age, BMI, albumin levels, NAC, operation procedure, operative time, perioperative blood transfusion, and tumor stage potentially affect the completeness of PAC (all P < 0.05)." (PMID 35769709, 2022). "The tumor growth inhibition rate (TGI, 81.1%) of FLQY2-SD (1.5 mpk, p.o./QW) in tumor-bearing mice after oral administration was higher than that of albumin-bound Paclitaxel (15 mpk, i.v./Q4D) and Irinotecan hydrochloride (100 mpk, i.p./QW)." (PMID 36064403, 2022). "The PCR results showed that ALB, ANGPTL7, IL6, and NGB were down-regulated in the BC tumor tissues, and BLOC1S5-TXNDC5 was up-regulated in the BC tumor tissues." (PMID 35962042, 2022). "Largest tumor size (LTS), serum albumin (ALB), total bilirubin (TBil), and serum creatinine were identified as independent predictors, which were used to establish a 30-day survival prediction model." (PMID 36376820, 2022). "Male ratio, leukocyte count, hemoglobin level, albumin level, ALBI grade, AFP level, main tumor size, BCLC stage, and tumor thrombus were different among the three groups (p < 0.05)." (PMID 35664791, 2022). "Based on previous studies, several pretreatment serum inflammatory markers including platelet–lymphocyte ratio (PLR), CRP albumin ratio (CAR), and systemic inflammatory response index (SIRI) are used to predict tumor progression and prognosis." (PMID 35198443, 2022). "We aimed to develop and validate a new prognostic model based on tumor burden score (TBS) and albumin–bilirubin (ALBI) grade for HCC." (PMID 35158917, 2022). "The conjugates were shown to interact with serum albumin, as well as presented some cytotoxicity against the MCF-7 tumor cell line by induction of autophagy." (PMID 35164267, 2022). "In particular, ICG-loaded human serum albumin (HSA-ICG) nanoparticles showed enhanced cellular uptake and tumor-targeting properties due to the expressed albumin receptors of cancer cells." (PMID 35454950, 2022). "rNACT was significantly correlated with inflammatory factors and clinical variables, namely, platelet-to-lymphocyte ratio (PLR), neutrophil-to-lymphocyte ratio (NLR), neutrophil-to-albumin ratio (NAR), lymphocyte-to-monocyte ratio (LMR), and tumor size." (PMID 35425697, 2022). "A non-therapeutic nuclear medicine agent, technetium-99m macro-aggregated albumin (MAA), is injected into the liver artery(ies) supplying the tumor(s) for simulating the distribution of the radioactive microspheres." (PMID 35448170, 2022). "Hemoglobin, serum albumin and creatinine, the CD4+/CD8+ ratio, and tumor size were entered into Cox regression analyses." (PMID 35804319, 2022). "Because albumin conjugation has been shown to extend the half-life of the IFNβ, we explored whether a single s.c. administration of Alb-IFNβ with E7 peptide in tumor-bearing mice can elicit E7-specific CD8 +T cell-mediated immune responses and enhanced DC activity." (PMID 35459734, 2022). "Laboratory data such as albumin, CEA, various blood cell levels, and MRI related data such as tumor regression grade assessed by magnetic resonance imaging (mrTRG) were collected from the included patients one week prior to NCRT." (PMID 36016621, 2022). "In this study, we generated H11 conjugated with an anti-serum albumin VHH and examined its potential in promoting anti-tumor immunity in other syngeneic models." (PMID 35237846, 2022). "In the derivation cohort, the area under ROC curve of GAR, ALB, GGT, 8th TNM stage, MVI, Node invasion and Tumour number for OS was 0.727, 0.603, 0.638, 0.666, 0.537, 0.606 and 0.586, respectively." (PMID 35481993, 2022).